RAB3IL1 (RAB3A interacting protein like 1)
Description:
Guanine nucleotide exchange factor (GEF) which may activate RAB3A, a GTPase that regulates synaptic vesicle exocytosis. Promotes the exchange of GDP to GTP, converting inactive GDP-bound Rab proteins into their active GTP-bound form. May also activate RAB8A and RAB8B.
Synonyms: GRAB
Tractability: Small molecule: a structure with a bound ligand is known. PROTAC: ubiquitination databases record sites on it.
Gene: Protein-coding gene on chromosome 11 (61,897,232 to 61,920,269, reverse strand). Ensembl gene ENSG00000167994.
Subcellular location (Human Protein Atlas): Centriolar satellite; Cytosol
Pathways (Reactome):
Vesicle-mediated transport: RAB GEFs exchange GTP for GDP on RABs
Gene Ontology:
Molecular function: guanyl-nucleotide exchange factor activity; identical protein binding; protein binding
Cellular component: cytosol
Genetic constraint (gnomAD): Loss-of-function variants: 37 observed, 42.21 expected, observed/expected ratio (o/e) 0.88, 90% interval 0.67 to 1.15. The upper end of that interval is the gene's LOEUF score, 1.15, which puts it in group 5 of 6, group 1 being the genes least tolerant of losing a copy. Missense variants: 484 observed, 470.91 expected, observed/expected ratio (o/e) 1.03, 90% interval 0.95 to 1.11. Synonymous variants: 193 observed, 193.93 expected, observed/expected ratio (o/e) 1, 90% interval 0.88 to 1.12.
Homologues: Orthologues: chimpanzee RAB3IL1 (100% identical), macaque RAB3IL1 (91% identical), pig RAB3IL1 (88% identical), rabbit RAB3IL1 (88% identical), dog RAB3IL1 (87% identical), mouse Rab3il1 (86% identical), rat Rab3il1 (85% identical), guinea pig RAB3IL1 (79% identical), tropical clawed frog rab3il1 (62% identical), zebrafish rab3il1 (58% identical), Caenorhabditis elegans F54C9.11 (31% identical). Paralogues in human: RAB3IP (53% identical).
Diseases named in the same sentence as RAB3IL1 in open-access papers:
RAB3IL1 is named in the same sentence as 11 diseases in open-access papers, as found by Europe PMC text mining. Sharing a sentence is not in itself a finding about the gene and the disease. The quoted sentences say what the papers report.
cancer (2 papers, 2023 to 2024). A tumor composed of atypical neoplastic, often pleomorphic cells that invade other tissues. "The rationale for the selection of the genes, HKDC1, RAB3IL1, RAB39B, FTH1, and FAM213A, is their potential pro-tumorigenic roles in other cancer types." (PMID 37082446, 2023).
RAB3IL1 also shares sentences with these, for which no sentence is quoted: tumor (3 papers); amyloidosis (1); brain injury (1); Cerebral ischemia (1); cervical cancer (1); Cognitive impairment (1); Hypertension (1); infection (1); kidney damage (1); Stroke (1).